EPHX4 (epoxide hydrolase 4)
Synonyms: ABHD7; EH4; EPHXRP; FLJ90341
Tractability: Antibody: UniProt predicts a signal peptide or a membrane-spanning region.
Gene: Protein-coding gene on chromosome 1 (92,029,475 to 92,063,538, forward strand). Ensembl gene ENSG00000172031.
Subcellular location: Membrane
Subcellular location (Human Protein Atlas): Vesicles
Gene Ontology:
Molecular function: protein binding; catalytic activity; epoxide hydrolase activity
Cellular component: membrane
Genetic constraint (gnomAD): Loss-of-function variants: 22 observed, 33.75 expected, observed/expected ratio (o/e) 0.65, 90% interval 0.47 to 0.93. The upper end of that interval is the gene's LOEUF score, 0.93, which puts it in group 3 of 6, group 1 being the genes least tolerant of losing a copy. Missense variants: 331 observed, 389.54 expected, observed/expected ratio (o/e) 0.85, 90% interval 0.78 to 0.93. Synonymous variants: 142 observed, 142.67 expected, observed/expected ratio (o/e) 1, 90% interval 0.87 to 1.14.
Homologues: Orthologues: chimpanzee EPHX4 (99% identical), dog EPHX4 (94% identical), guinea pig EPHX4 (94% identical), rabbit EPHX4 (93% identical), pig EPHX4 (90% identical), mouse Ephx4 (88% identical), rat Ephx4 (87% identical), tropical clawed frog ephx4 (73% identical), zebrafish ephx4 (68% identical), Caenorhabditis elegans F10D2.10 (12% identical), Caenorhabditis elegans Y73C8B.2 (12% identical), Caenorhabditis elegans Y73C8B.3 (12% identical), and 10 more. Paralogues in human: EPHX3 (44% identical), EPHX2 (32% identical), ABHD8 (21% identical), ABHD5 (20% identical), ABHD4 (18% identical), ABHD6 (17% identical), BPHL (17% identical), MEST (16% identical), SERHL2 (15% identical), ABHD11 (15% identical), ABHD14A (14% identical), ABHD14B (12% identical).
Diseases named in the same sentence as EPHX4 in open-access papers:
EPHX4 is named in the same sentence as 11 diseases in open-access papers, as found by Europe PMC text mining. Sharing a sentence is not in itself a finding about the gene and the disease. The quoted sentences say what the papers report.
colon cancer (2 papers, 2013 to 2015). "We thus compared with the same gene expressions (up-regulated transcripts: SLC16A4, DSC3, ALDOB, EPHX4, ARHGAP24; and down-regulated transcripts (MS4A12, TMIGD1, CASP5) in 5 colon cancer lines: HCT 116, Caco2, HT-29, Lovo, and C32." (PMID 25929336, 2015).
rectal cancer (2 papers, 2019 to 2023). A primary or metastatic malignant neoplasm that affects the rectum. "This led to the identification of genes with increased H3K27ac, i.e., RIPK2, FOXQ1, KRT23, and EPHX4, which were also highly upregulated in primary rectal cancer in an independent dataset." (PMID 31404997, 2019). "EPHX4 expression levels are highly upregulated in primary rectal cancer." (PMID 37309005, 2023).
amoebiasis (1 paper, 2024). "We also found five KEGG pathways related to the dysregulation of EPHX4 mRNA expression, which comprised with protein processing in endoplasmic reticulum, amoebiasis, viral protein interaction with cytokine and cytokine receptor, lysosome and natural killer cell mediated cytotoxicity." (PMID 38663041, 2024).
colorectal cancer (1 paper, 2015). A primary or metastatic malignant neoplasm that affects the colon or rectum. "Fourth was epoxide hydrolase 4 (EPHX4), an enzyme involved in carcinogen inactivation with reduced levels of epoxide hydrolase activity and linked to increased colorectal cancer risk." (PMID 25929336, 2015).
laryngeal carcinoma (1 paper, 2024). Carcinoma that arises from the laryngeal epithelium. "We also analyzed the correlation between immune cell infiltration levels and EPHX4 gene copy number in laryngeal cancer." (PMID 38663041, 2024). "We observed that EPHX4 expression and its survival assays in laryngeal cancer specimens based on The Cancer Genome Atlas (TCGA) cohorts." (PMID 38663041, 2024). "Finally, we conducted in vitro assay to evaluate the functions of EPHX4 in laryngeal cancer cell line." (PMID 38663041, 2024). "Our research results suggest that EPHX4 may be a potential immunotherapy target for laryngeal cancer." (PMID 38663041, 2024). "EPHX4 is highly expressed in laryngeal cancer specimens and has a poor prognosis." (PMID 38663041, 2024). "Finally, Cell experiments indicate that EPHX4 could promote laryngeal cancer cell line proliferation, colony formation and invasion." (PMID 38663041, 2024).
lung adenocarcinoma (1 paper, 2025). A carcinoma that arises from the lung and is characterized by the presence of malignant glandular epithelial cells. "This research utilized an extensive methodology to examine the function of EPHX4 in lung adenocarcinoma (LUAD) by drawing on information from The Cancer Genome Atlas (TCGA) and the Gene Expression Omnibus (GEO) repositories." (PMID 40507905, 2025). "Accordingly, the potential research value of EPHX4 in lung adenocarcinoma, and potentially other cancers, warrants further investigation." (PMID 40507905, 2025). "An analysis of methylation patterns demonstrated that EPHX4 exhibited diminished methylation levels in lung adenocarcinoma (LUAD) tissues when contrasted with normal lung tissues." (PMID 40507905, 2025). "Thus, EPHX4 may enhance the expression of immune checkpoints, facilitating immune evasion in lung adenocarcinoma and contributing to its progression." (PMID 40507905, 2025).
lung squamous cell carcinoma (1 paper, 2025). "A ROC analysis indicated that EPHX4 possesses considerable discriminative capability in the clinical identification of both LUAD and lung squamous cell carcinoma (LUSC), with expression levels proficiently differentiating tumor tissues from their normal counterparts." (PMID 40507905, 2025).
tumor (7 papers, 2013 to 2025). "Ultimately, the tumor mutational burden (TMB) was elevated in the group exhibiting high EPHX4 expression compared to their low-expression counterparts." (PMID 40507905, 2025). "Additionally, EPHX4 was involved in pivotal tumor-associated pathways, particularly cell cycle regulation." (PMID 40507905, 2025). "Firstly, although we performed in vitro assays to verify the function of EPHX4 in tumor progression, our results were derived from a public database." (PMID 38663041, 2024). "Our results showed the potential role of EPHX4 in LSCC would help us to understand the underlying molecular mechanism between EPHX4 and the tumor-immune microenvironment in LSCC." (PMID 38663041, 2024). "Further exploration of EPHX4 may provide potential strategies aimed at reprogramming TAMs to enhance anti-tumor immunity in LUAD." (PMID 40507905, 2025). "Our result suggests that EPHX4 may contribute to a tumor-promoting immune environment, potentially serving as a therapeutic target to modulate Th2 responses in LUAD." (PMID 40507905, 2025). "Moreover, data from the UALCAN database suggested that the methylation levels of the EPHX4 promoter were decreased in tumor tissues, a finding that was supported by the MethSurv database." (PMID 40507905, 2025). "The positive association between EPHX4 expression and macrophage infiltration suggests that EPHX4 may modulate macrophage towards a phenotype that supports tumor growth and immune evasion." (PMID 40507905, 2025). "EPHX4′s functional role in tumor biology remains largely unexplored in previous literature." (PMID 40507905, 2025). "Subsequent investigations can refer to our findings and explore EPHX4 with further experimental studies to delineate the specific mechanisms by which EPHX4 influences tumor biology and to evaluate its clinical utility, ultimately contributing to improved patient outcomes." (PMID 40507905, 2025). "In our study, it is biologically plausible to speculate that EPHX4 might influence the efficacious of NK-target therapy, further exploring the molecular function of EPHX4 in NK cells is helpful to boost NK-target tumor immunity." (PMID 38663041, 2024). "Finally, the lower Immune Profile Score (IPS) observed in the high EPHX4 expression group indicates that EPHX4 could impact tumor immune evasion mechanisms, potentially reducing responses to anti-CTLA-4 and anti-PD-1 therapies." (PMID 40507905, 2025). "To explore the expression pattern of EPHX4, we performed an IHC staining to analyze its expression in LSCC tumor tissues, EPHX4 protein was expressed at significantly higher levels in LSCC tumor tissues than in paired normal tissues." (PMID 38663041, 2024). "However, to our surprise, our results demonstrated that EPHX4 was significantly negatively correlated with CD274, PDCD1, IDO1 and LAG3, which all attenuate anti-tumor immunity and escape destruction by the immune system." (PMID 38663041, 2024). "Our analysis demonstrated that MYLK2, FAM83D, STC2, CCDC112, EPHX4 and MMP1 were differentially expressed between tumor and normal tissues, with higher expression in tumor tissues than in normal tissues (p < 0.0001)." (PMID 37309005, 2023). "Thus, we sought to not only confirm the differential expression of RIPK2, FOXQ1, KRT23 and EPHX4 in the investigated tumor samples, but also examine whether the differential epigenetic marking of the genes was, indeed, specific for tumor cells and not from stromal contamination." (PMID 31404997, 2019). "However, when we investigated EPHX4 and ANKRD22 expression in different pathological tumor stages, EPXH4 did not statistically significantly express across cancer stages, F = 1.06, p > 0.05, whereas ANKRD22 showed that its presence between tumor stages was significant with F = 4.8 and p < 0.01." (PMID 40225855, 2025).
cancer (4 papers, 2013 to 2025). A tumor composed of atypical neoplastic, often pleomorphic cells that invade other tissues. "The results showed that EPHX4 expression was obviously associated with immunoinhibitors in different kinds of cancer." (PMID 38663041, 2024). "Using data sourced from The Cancer Genome Atlas (TCGA) and Genotype-Tissue Expression (GTEx) databases, which were subsequently validated by the Gene Expression Omnibus (GEO), we analyzed levels of EPHX4 expression, mutation, and methylation in tumors versus normal tissues." (PMID 40507905, 2025). "Nonetheless, limited research has explored the expression and clinical significance of EPHX4 in cancer." (PMID 40507905, 2025). "This reveals a potential mechanism through which EPHX4 promotes cancer, offering insights and a basis for future research." (PMID 40507905, 2025). "To further investigate the association EPHX4 expression with immunomodulators, we first studied the relationship between EPHX4 expression and immunoinhibitors among various human cancer types." (PMID 38663041, 2024). "To the beginning, we analyzed the relationship between the expression level of EPHX4 and the Overall Survival (OS) of EPHX4 in LSCC patients from The Cancer Genome Atlas (TCGA) datasets." (PMID 38663041, 2024). "All these findings, together suggested that EPHX4, might act an important role in the cancer immune microenvironment of LSCC." (PMID 38663041, 2024). "Above all results verified that an important role of EPHX4 in cancer immune microenvironment." (PMID 38663041, 2024). "The role of Epoxide Hydrolase-4 (EPHX4), a member of epoxide hydrolase family, has not been investigated in cancer." (PMID 38663041, 2024).
EPHX4 also shares sentences with these, for which no sentence is quoted: laryngeal squamous cell carcinoma (1 paper); rheumatoid arthritis (1).